MAPT (microtubule associated protein tau)
Diseases named in the same sentence as MAPT in open-access papers (continued):
Sharing a sentence is not in itself a finding about the gene and the disease.
neurodegenerative disease (continued). "Many neurodegenerative diseases are caused by mutations around the MAPT exon 10 – intron 10 junction, and there are no approved therapeutics that target this junction." (PMID 35695373, 2022). "We present this hypothesis cautiously due to CRHR1’s location in a linkage disequilibrium block containing genes like MAPT, which may be involved in neurodegenerative diseases and cortical anatomy." (PMID 35947372, 2022). "In previous analyses on Finns, the MAPT variation, including the H1/H2 haplotype, has been shown to associate only weakly or not at all with different forms of neurodegenerative diseases." (PMID 34927275, 2022). "The accumulation of MAPT is related to neurodegenerative diseases." (PMID 35252219, 2021). "While this haplotype and locus is interesting as it hosts the MAPT gene that encodes tau protein, the exact molecular mechanism why the MAPT locus is associated with neurodegenerative disease is not understood." (PMID 33804213, 2021). "Neurodegenerative disease can increase astrocytic MAPT expression, suggesting that reactive astrogliosis could lead to astrocytes making more tau." (PMID 33757579, 2021). "High expression levels of MAPT may lead to an increase in the prevalence of neurodegenerative diseases; the methylation of MAPT promoter is particularly related to PD." (PMID 32617144, 2020). "In frontotemporal dementia and parkinsonism linked to chromosome 17 (FTDP-17), mutations in microtubule-associated protein tau (MAPT) alone can cause neurodegenerative disease in the absence of Aβ." (PMID 31126115, 2019). "We identified 70 additional novel and missense variants in other genes, such as MAPT, GRN, CSF1R, and PRNP, related to neurodegenerative diseases, which may represent overlapping clinical and neuropathological features with AD." (PMID 31182772, 2019). "The relationship of neurofibrillary tangles to cell death is not understood, though mutations in the tau gene (MAPT) on chromosome 17 lead to tau accumulation and neuronal loss in other neurodegenerative diseases." (PMID 31375134, 2019). "Mutations of MAPT, the tau gene, were discovered in 1998 and co-segregate with the disease in FTDP-17, providing unequivocal evidence that abnormalities in tau alone are enough to cause neurodegenerative disease." (PMID 30356756, 2018). "Subjects were screened for C9orf72 repeat expansions, GRN and MAPT mutations, and, if negative, mutations in other neurodegenerative disease genes, by whole-exome sequencing (WES) (n = 108), including WES-based copy-number variant (CNV) analysis." (PMID 28749476, 2018). "Unfortunately, some studies showed obvious association of MAPT variants with neurodegenerative diseases, while others showed none." (PMID 28402959, 2017). "The MAPT gene is of central importance to a number of neurodegenerative diseases." (PMID 28689993, 2017). "MAPT, a common DEHP, E2 and NRF1 target genes are associated with neurodegenerative disease." (PMID 27983596, 2016). "We have shown that the regional expression of the MAPT gene in health is associated with regions of high connectivity, which predict the functionally relevant loss of connectivity in PSP, a neurodegenerative diseases associated strongly with progressive misfolding and aggregation of the protein tau." (PMID 27697694, 2016). "CisSNP alleles associating with lower brain MAPT levels were associated with lower AD risk, similar to PD and PSP GWAS, which may suggest a common mechanism for these neurodegenerative diseases." (PMID 22685416, 2012). "ESCRT-III might be a link between autophagy and MAPT/TAU in neurodegenerative diseases." (PMID 33151516, 2021). "However, 1H MRS from the medial frontal lobe voxel was more sensitive than 1H MRS from the PCC voxel in the asymptomatic MAPT mutation carriers, characterized by decreased NAA/Cr and NAA/mI ratios, suggesting specific regional involvement in neurodegenerative diseases." (PMID 32184751, 2020).
neurodegenerative disease (continued). "Finally, we also evaluated whether some other well-known neurodegenerative disease-related genes are affected in our MAPT IVS10+16 mutant NPCs and neurons, compared with the control." (PMID 30057263, 2018). "Given that a higher level of MAPT expression may potentially lead to increased neurodegeneration it can be hypothesised that mechanisms regulating the expression of MAPT could contribute to neurodegenerative disease." (PMID 27336847, 2016). "In conclusion, we provide preliminary evidence that the MAPT locus may play a role in regulating the sense of smell in older adults and therefore offer a potential genetic link between poor sense of smell and major neurodegenerative diseases." (PMID 26632684, 2015). "However, larger screening of the MAPT gene has shown that copy number gains have not so far been implicated in neurodegenerative diseases." (PMID 24649381, 2014). "Notably, mutations in SG-associated genes—including MAPT, TARDBP (TDP-43), FUS, ATXN2, TIA1, and HNRNPA1—have been shown to disrupt SG dynamics, impair disassembly, and enhance aggregation propensity, thereby contributing to neurodegenerative disease pathogenesis." (PMID 41278186, 2025). "The results of this study demonstrated the regional distribution of MAPT and SYUA for the first time, adding new information about the pathogenesis and vulnerability of these two neurodegenerative diseases in the cingulate cortex." (PMID 34763096, 2022). "Thus, the molecular mechanisms involved in neurodegenerative disease risk are not yet clear, but both MAPT increased expression and preferential inclusion of exon 10 could play a role." (PMID 35694745, 2022). "To investigate the role of MGLs in neurodegenerative diseases, we developed a human FTLD in vitro model in which hiPSC-derived MAPT-mutant neurons were cocultured with MGLs." (PMID 36251998, 2022). "MAPT haplotypes H1H1, H1H2 and H2H2 are possibly the most studied haplotypes in neurodegenerative disease research." (PMID 33804213, 2021). "Detailed biochemical and genetic studies about APP, MAPT and PTEN molecular processing will be crucial to the development of therapeutic targets to treat many neurodegenerative diseases." (PMID 24688734, 2013). "The proteins upregulated across multiple neurodegenerative diseases within cortical layer I include phosphorylated TDP-43 (significant change identified in C9ORF72 and GRN) and phosphorylated tau S214 (significant change identified in AD and MAPT)." (PMID 40476255, 2025). "A sample of postmortem brains, including 95 PD cases and 81 controls without neurodegenerative diseases, has been genotyped for the MAPT haplotype." (PMID 36906636, 2023).
cancer (49 papers, 2006 to 2026). A tumor composed of atypical neoplastic, often pleomorphic cells that invade other tissues. "The AD proteinopathic tau protein is normally involved in the stabilization of microtubules, and mutated tau (i.e., resulting from a mutation in the MAPT gene) is reported to influence the spread of cancer cells and cell growth." (PMID 41241298, 2025). "α-synuclein, PTEN, PINK1, DJ-1 (PARK7), LRRK2, and tau (MAPT) are critical for neuronal integrity, yet their mutations or aberrant expression are also observed in various cancers." (PMID 41516242, 2025). "MAPT expression associated with key cancer hallmarks including inflammation, proliferation, and epithelial to mesenchymal transition, showing cancer-specific patterns." (PMID 37730697, 2023). "Our study highlights, however, a strong association of MAPT expression with two other classes of cancer drugs, HDAC inhibitors, and several kinase inhibitors." (PMID 37730697, 2023). "In our characterization of MAPT’s role in cancer, we also investigated its association with drug response in cell lines derived from 22 different cancer types." (PMID 37730697, 2023). "After exploring genes and pathways linked to MAPT expression, we thoroughly analyzed the association of MAPT with cancer survival." (PMID 37730697, 2023). "Altogether, we described how several pathways and genes are associated with MAPT expression in all main cancer types." (PMID 37730697, 2023). "The Microtubule-associated protein Tau is expressed in different cancers; however, its role and prognostic value are still debated." (PMID 34830972, 2021). "It has been reported that the risk of developing cancer is significantly higher in families affected by genetic tauopathies and MAPT is frequently methylated, with hypermethylation associated with a poorer prognosis, in CRC patients." (PMID 34502304, 2021). "Overexpression of MAPT in colorectal, breast, and gastric cancers was associated with tumor progression and poor prognosis." (PMID 34299042, 2021). "Overall, it appears that MAPT mutations are driving factors for neurodegenerative disorders as well as some cancer forms." (PMID 33207722, 2020). "A recent analysis of cancer incidence in carriers of FTDP-17 MAPT mutations showed increased risk of developing cancer." (PMID 33207722, 2020). "MAPT overexpression has also been linked to resistance to taxane-based therapies in various other cancer types." (PMID 30823906, 2019). "MAPT, which is associated with paclitaxel resistance in several cancers including EOC, was more highly expressed in SKOV3-C1 cells than in SKOV3-NV cells (2.47-fold, p = .00702)." (PMID 27184254, 2016). "Since the variable association with survival in different cancer types, we evaluated whether this could be related to a change in the biological network associated with MAPT expression." (PMID 37730697, 2023).
cancer (continued). "In summary, MAPT expression levels are associated with major cancer hallmarks, with some commonalities across groups of cancer types but a high degree of tumor specificity, indicating that the biological networks that include MAPT are highly context-specific." (PMID 37730697, 2023). "Overall, our data indicate the existence of a causal link between the expression of the CDA and MAPT genes that could be exploited in the development of new anti-cancer strategies." (PMID 28947735, 2017). "Single-cell RNA sequencing revealed MAPT upregulation in T cells, PLXDC1 enrichment in cancer-associated fibroblasts, and mild STC2 elevation in tumor-associated macrophages and endothelial cells." (PMID 41755885, 2026). "The genes BLK, FAM167A, STAT1, STAT4, TNPO3, and TNIP1 are associated with AIDs, and CDC37, DDX6, MAPT, STAT1, STAT4, and UBE3A are associated with cancers." (PMID 40429780, 2025). "The genes BLK, CDC247, CSK, IRF5, STAT1, STAT4, and TNIP1 are associated with AIDs, and CDC37, DDX6, HSPA6, MAPT, PPIB, STAT1, and STAT4 are associated with cancers." (PMID 40429780, 2025). "In fact, several studies reported a correlation between MAPT mRNA expression and survival in various cancer types." (PMID 40319030, 2025). "For example, this is the case for estrogen response genes (e.g., ESTROGEN_RESPONSE_EARLY) specifically enriched in BRCA, with ESR1 and PGR highly correlated with MAPT in this cancer type." (PMID 37730697, 2023). "Only a low-moderate correlation was observed in all cases, suggesting only a weak link between the expression levels and the potential relevance of MAPT within cancer biological networks." (PMID 37730697, 2023). "To strengthen the emerging evidence for the role of MAPT in cancer, we performed a pan-cancer in silico analysis to define the landscape of pathways, genes, and drug treatments associated with MAPT expression." (PMID 37730697, 2023). "From the MAPT-all gene correlation analysis, we identified 809 genes with a significant correlation with MAPT in at least one cancer type." (PMID 37730697, 2023). "The impact of MAPT KO on viability was cancer-specific but overall, a decrease in viability is prevalently observed, except for rhabdoid cell lines." (PMID 37730697, 2023). "In the EMT dataset, some correlations with MAPT varied similarly in a defined cancer type whereas they changed oppositely in another cancer type." (PMID 37730697, 2023). "The associations of MAPT expression with genes encoding for proteins involved in proliferation, EMT, and inflammation were very variable among cancers." (PMID 37730697, 2023). "To shed light on the relevance of Tau in cancer, we evaluated MAPT gene expression values in 32 distinct cancer types mining the TCGA pan-cancer cohort." (PMID 37730697, 2023). "Overall, our findings indicate that the MAPT gene is a potential major player in multiple types of cancer." (PMID 37730697, 2023). "Association between MAPT expression and resistance to kinases inhibitors was also detected in lymphocytes (PI3K) and bone and uterus-derived cancer cell lines (Aurora kinase)." (PMID 37730697, 2023). "Taken together, these studies indicate that MAPT clearly plays a complex and possibly cancer-specific role in different cancers, which warrants more in-depth, well-designed investigations." (PMID 34406386, 2021). "Previous investigation identified that MAPT is overexpressed in certain cancers, and participate in the resistance of various tumours to taxane drugs, and its specific mechanism of action still needs further study." (PMID 33962640, 2021).
cancer (continued). "Clear-cut heterogeneity was even found in some TMA spots and a thorough analysis of all cancer-containing tissue blocks of three of our cancers with high MAPT expression on TMA spots always revealed both MAPT positive and MAPT negative cancer areas." (PMID 30823906, 2019). "Because heterogeneous findings were occasionally seen in TMA spots, three cancers with high MAPT expression were selected for analysis of intratumoral heterogeneity." (PMID 30823906, 2019). "In tumors, MAPT staining was seen in 8.2% (1004 / 12,313) samples and was considered low in 7.1% and high in 1.1% of cancers." (PMID 30823906, 2019). "By contrast, it seems that Tau/MAPT mRNA is enriched in those cancers in which it has a significant prognostic value, particularly for breast and kidney tumors." (PMID 31551755, 2019). "Aberrant expression of MAPT has been reported for many cancer types such as gastric, breast, and colorectal cancer, and has been linked to adverse tumor features and poor prognosis in some of them." (PMID 30823906, 2019). "Most reports studying MAPT (microtubule-associated protein tau) and AUTS2 (autism susceptibility gene 2 protein) have focused on neural diseases and only a few studies have investigated their functions in cancer progression." (PMID 29215599, 2017). "For let-7e-3p, cancer-associated genes such as MAPK1 and EZH2 were among the negatively correlated genes, and PURA, ERCC1 and MAPT were among the positively correlated ones." (PMID 24257477, 2013). "Cell line HCC1569, which has a low MAPT expression, showed a low sensitivity to all four anti-cancer drugs, but its character is unclear." (PMID 20579400, 2010). "Cell line HCC1937, which has a low MAPT expression, showed a low sensitivity to all four anti-cancer drugs." (PMID 20579400, 2010). "Recently, the function of MAPT in cancer has been investigated." (PMID 40836964, 2025). "Overall, these data highlighted that MAPT expression may represent an informative predictor of drug response in multiple cancer types." (PMID 37730697, 2023). "Our analysis to chart the relevance of MAPT in cancer continued in pan-cancer pre-clinical data." (PMID 37730697, 2023). "MAPT expression was next correlated with all expressed genes in each cancer type." (PMID 37730697, 2023). "First, we evaluated MAPT expression across cancer cell lines grouped by cancer type." (PMID 37730697, 2023). "Interestingly, we observed a positive pan-cancer correlation of MAPT with a large set of neuronal genes." (PMID 37730697, 2023). "Interestingly, MAPT is reported to play an essential role in mediating paclitaxel or taxane resistance in various cancers." (PMID 34406386, 2021). "An extensive body of literature suggested a possible role of the microtubule-associated protein Tau in chromatin functions and/or organization in neuronal, non-neuronal, and cancer cells." (PMID 34722523, 2021). "It is also known that MAPT interacts with other cancer related proteins and pathways." (PMID 30823906, 2019). "The existing data suggest a general role of MAPT protein in cancer." (PMID 30823906, 2019). "It is unknown why MAPT exerts a different impact on tumor cell aggressiveness in different cancer types." (PMID 30823906, 2019). "Moreover, an association was found between MAPT expression and PTEN deletions, with 19% MAPT positivity in 948 PTEN deleted cancers but only 7% MAPT positivity in 3895 tumors with normal PTEN copy numbers (p < 0.0001)." (PMID 30823906, 2019).